CNPY2 (canopy FGF signaling regulator 2)
Diseases named in the same sentence as CNPY2 in open-access papers (continued):
Sharing a sentence is not in itself a finding about the gene and the disease.
Sepsis (1 paper, 2025). Sepsis is defined as life-threatening organ dysfunction caused by a dysregulated host response to infection. "Related patterns were observed for FBXO31, PTCD3, and CNPY2, which also demonstrated significant correlations with multiple immune cell subsets, underscoring their collective involvement in sepsis immunopathology." (PMID 41194984, 2025). "Differential gene expression and co-expression network analyses identified five key genes—CDC25B, DPP7, FBXO31, PTCD3, and CNPY2—that play critical roles in immune response and cellular regulation in sepsis and T2DM." (PMID 41194984, 2025). "Further refinement by intersecting these genes with previously identified DEGs yielded five candidate genes: CDC25B, DPP7, FBXO31, PTCD3, and CNPY2, These genes emerged as promising biomarkers for both T2DM and sepsis, warranting further investigation into their functional roles." (PMID 41194984, 2025).
spinal cord ischemia (1 paper, 2021). Reduced blood flow to the spinal cord which is supplied by the anterior spinal artery and the paired posterior spinal arteries. "Our previous research also found that the CNPY2-ERS apoptosis pathway participated in the process of spinal cord ischemia-reperfusion injury." (PMID 33995012, 2021).
tumor (11 papers, 2017 to 2026). "Similarly, we previously assessed the associations between CNPY2 isoform 2 expression and various clinicopathological parameters, including tumor size and clinical stage." (PMID 30070972, 2018). "CNPY2 is overexpressed in multiple tumor types, where its abundance correlates with poor prognosis by promoting proliferation, invasion, and tumor microenvironment remodeling." (PMID 41596760, 2026). "We begin by examining the structure and function of CNPY2, its diverse roles in specific solid tumors, and its influence on the tumor microenvironment." (PMID 40001982, 2025). "This review aims to provide a comprehensive overview of CNPY2’s functions in solid tumors, with a particular focus on its mechanisms of action, its impact on the tumor microenvironment, and its potential as a biomarker and therapeutic target." (PMID 40001982, 2025). "Large-scale prospective trials are now needed to fully characterize circulating CNPY2 levels across various solid tumors and evaluate its potential for monitoring tumor progression or therapy response via non-invasive sampling." (PMID 40001982, 2025). "Beyond its metabolic functions, CNPY2 plays a critical role in immune regulation within the tumor microenvironment." (PMID 40001982, 2025). "Studies have shown that CNPY2 can enhance angiogenesis and stimulate the proliferation and growth of smooth muscle cells under hypoxic conditions within the tumor microenvironment." (PMID 40001982, 2025). "A 2018 study in HCC cells showed that CNPY2 interacts directly with the tumor microenvironment, including various immune cells, such as T cells, as well as extracellular proteins and cytokines that contribute to HCC proliferation." (PMID 40001982, 2025). "Significant factors by univariate analysis included Ki-67 ≥ 8.2% (p = 0.009), tumor size ≥ 42 mm (p = 0.007), vascular invasion (p = 0.009), lymphatic invasion (p = 0.012) and CNPY2 positive (p = 0.010)." (PMID 29849941, 2018). "In the multivariate analysis, the independent predictors of liver RFS were CNPY2 positivity (hazard ratio (HR): 6.19, 95% confidence interval (95% CI): 1.47–42.79, p = 0.011) and tumor size ≥ 42 mm (HR: 4.63, 95% CI: 1.03–23.23, p = 0.045)." (PMID 29849941, 2018). "The present study demonstrated that the expression of CNPY2 and tumor size were independent predictors of liver RFS." (PMID 29849941, 2018). "In the multivariate analysis, the independent predictors of liver RFS were CNPY2 positivity (HR: 6.19, 95 % CI: 1.47–42.79, p = 0.011) and tumor size ≥ 42 mm (HR: 4.63, 95 % CI: 1.03–23.23, p = 0.045)." (PMID 29849941, 2018). "While some cancers may share common pathways for CNPY2-driven tumor initiation and proliferation, others appear to utilize distinct mechanisms." (PMID 40001982, 2025). "The study also found that an Ezrin-interacting protein signature could be used to predict tumor recurrence and survival outcomes, highlighting CNPY2’s potential role in ESCC progression." (PMID 40001982, 2025). "In short, understanding the role of CNPY2 could lead to improved care for patients by offering new ways to slow down or stop tumor growth, ultimately reducing the impact of cancer on society." (PMID 40001982, 2025). "By contributing to maladaptive unfolded protein response signaling, CNPY2 could serve as a novel checkpoint in T cell biology within the tumor microenvironment." (PMID 40001982, 2025). "Additionally, CNPY2 influences the tumor microenvironment, impacting immune function and metastatic potential." (PMID 40001982, 2025). "CNPY2 expression is also influenced by hypoxia, a condition common in tumor microenvironments." (PMID 40001982, 2025).
tumor (continued). "Future studies in co-culture models or patient-derived xenografts may help clarify whether CNPY2 expression in stromal cells mirrors or enhances the pro-tumoral roles observed in tumor cells themselves." (PMID 40001982, 2025). "Notably, knocking out CNPY2 in HCC cell lines reduced tumor hemorrhage, which typically protects tumors from immune system attacks, underscoring CNPY2’s role in linking ER-stress-mediated survival responses to tumor microenvironment modulation." (PMID 40001982, 2025). "In addition, we found that the two isoforms of CNPY2 mRNA were significantly increased in 5 CRC tissues compared with the paired tumor-adjacent normal tissues (P < 0.01)." (PMID 29135454, 2017). "Given CNPY2’s role in regulating ER stress and hypoxia responses, one can hypothesize that its expression in CAFs—if elevated—could reshape the stromal “niche”, fostering further tumor invasiveness and immune suppression." (PMID 40001982, 2025). "However, similar to mouse HCCs, CNPY2-positive nuclear endosomes also found in human tumor cells." (PMID 34298825, 2021). "Canopy FGF signaling regulator 2 (CNPY2) has emerged as a critical player in cancer biology, with increasing evidence pointing to its pivotal role in tumor development and progression." (PMID 40001982, 2025). "CNPY2 is more abundantly expressed in CRC cell lines and tumor tissues compared to normal colonic epithelial cells and tumor-adjacent normal tissues." (PMID 29135454, 2017). "Therefore, we propose here that induction of ER stress and unfolded protein response by CNPY2 due to its ability to suppress proteolysis, and stabilize actomyosin complexes may play roles and promote the growth of podia during invasion and metastasis of tumor cells." (PMID 34298825, 2021). "Unexpectedly, high levels of CNPY2 isoform 2 did not indicate a larger tumor size or advanced TNM stage." (PMID 30070972, 2018). "The expression of miR-545-5p and CNPY2 in tumor tissues was assessed and the results showed that knockdown of LINC00342 significantly increased the expression levels of miR-545-5p (p < 0.01) and reduced the expression levels of CNPY2 (p < 0.01) in tumor tissues compared with negative control sh-NC." (PMID 34715819, 2021).
cancer (6 papers, 2018 to 2026). A tumor composed of atypical neoplastic, often pleomorphic cells that invade other tissues. "For example, MYLIP, an E3 ubiquitin kinase, is a key target of CNPY2 and is implicated in the development of several cancers." (PMID 40001982, 2025). "Beyond its diagnostic potential, targeting CNPY2 for cancer therapy can involve either directly inhibiting CNPY2 or focusing on downstream effectors." (PMID 40001982, 2025). "Researchers found that CNPY2 is involved in several processes that make cancer cells more aggressive and better able to avoid the body’s natural defenses." (PMID 40001982, 2025). "As a potential biomarker, CNPY2 shows promise for cancer detection and prognosis, particularly when used in combination with other markers." (PMID 40001982, 2025). "More detailed studies are needed to fully elucidate the molecular mechanisms of CNPY2 in different cancers." (PMID 40001982, 2025). "This review examines a protein called CNPY2, which is found in higher amounts in many types of cancer such as those affecting the kidney, liver, lung, and prostate." (PMID 40001982, 2025). "With continued innovation, it is conceivable that CNPY2-directed interventions will progress from early research stages to clinical testing, ultimately offering new hope for patients battling cancers that rely on this key regulator." (PMID 40001982, 2025). "A 2017 study showed that CNPY2 is released during ER stress, which activates the unfolded protein response, potentially improving cancer cell survival under these stressful conditions." (PMID 40001982, 2025). "Recent findings indicate that CNPY2 is upregulated in response to ER stress, driving pro-survival pathways in cancer cells." (PMID 40001982, 2025). "There is substantial potential for the development of cancer therapies targeting CNPY2 or its downstream effectors, and further exploration in this area is highly warranted." (PMID 40001982, 2025). "The findings position CNPY2 as an important player in cancer biology, especially in solid tumors, and highlight its potential as both a therapeutic target and biomarker." (PMID 40001982, 2025). "By consolidating the latest findings and identifying key areas for future research, this review seeks to foster a deeper understanding of CNPY2’s significance in cancer biology and its potential implications for cancer diagnosis and treatment." (PMID 40001982, 2025). "As research into CNPY2’s role in cancer has expanded rapidly in recent years, there is a pressing need to synthesize and critically evaluate the current state of knowledge." (PMID 40001982, 2025). "Understanding these diverse pathways further highlights CNPY2’s potential as a key regulator of cancer progression." (PMID 40001982, 2025). "The role of CNPY2 in cancer growth is thought to be mediated through various mechanisms, which can differ depending on the type of cancer." (PMID 40001982, 2025). "Each cancer type appears to utilize CNPY2 through distinct mechanisms, highlighting the protein’s versatility in promoting oncogenesis." (PMID 40001982, 2025). "Canopy FGF signaling regulator 2 (CNPY2) has emerged as a crucial player in cancer development by promoting cell proliferation, tissue repair, and angiogenesis." (PMID 40001982, 2025). "In the past decade, research into CNPY2 has significantly advanced our understanding of its role in various diseases, particularly cancer." (PMID 40001982, 2025). "Given that CNPY2 is overexpressed in various cancers, it has strong potential as a biomarker for both diagnosis and prognosis." (PMID 40001982, 2025). "Experimental validation through CNPY2 knockdown demonstrated reduced cancer cell survival, confirming its critical role in disease progression." (PMID 40001982, 2025). "Primarily, CNPY2 has been shown to influence angiogenesis, thereby regulating cancer cell growth, proliferation, and metastasis." (PMID 40001982, 2025).
cancer (continued). "CNPY2 has also emerged as an important factor for the regulation of cell proliferation and viability of tumors, by modulating cancer cell signaling." (PMID 39359687, 2024). "In contrast, transfection of a mouse CNPY2 (mCNPY2-Ds-Red) vector plasmid in Huh7 and HepG2 cancer cells, with subsequent accumulation of CNPY2 in the ER, resulted in significant increase in cancer cells survival." (PMID 34298825, 2021). "These examples illustrate that CNPY2 plays a role in multiple pathways across different cancers, each of which may rely on unique mechanisms to promote oncogenesis." (PMID 40001982, 2025). "Although direct evidence is currently lacking, it is plausible that CNPY2 also modulates other stromal components, including cancer-associated fibroblasts (CAFs)." (PMID 40001982, 2025). "While CNPY2’s presence in blood samples has been confirmed, including in healthy individuals and cancer patients, further investigation of its utility in liquid biopsy applications could enhance its clinical value." (PMID 40001982, 2025). "Additionally, we will discuss the emerging potential of CNPY2 as a biomarker for cancer detection and prognosis, as well as early efforts to target CNPY2 therapeutically." (PMID 40001982, 2025). "Overall, it is clear that CNPY2 is upregulated in various cancers and may contribute to tumorigenesis through different mechanisms." (PMID 40001982, 2025). "Furthermore, CNPY2 overexpression was shown to enhance the invasive and metastatic capabilities of these cancer cells." (PMID 40001982, 2025). "In line with our results, critical roles of CNPY2 in ER stress and unfolded protein response-related diseases such as metabolic disorders, inflammation and cancer through regulation of protein kinase R-like ER kinase (PERK)-C/EBP homologous protein (CHOP) pathway have been proposed." (PMID 34298825, 2021). "Although current preclinical data are promising, including both in vitro and in vivo studies, no clinical trials targeting CNPY2 inhibition are currently underway as a cancer treatment strategy." (PMID 40001982, 2025). "Structural analysis of CNPY2 interaction with UBE2D1 is required to improve our understanding of how CNPY2 inhibits MYLIP-UBE2D1 interaction, which may lead to development of new targeted therapy for cancer." (PMID 29707137, 2018).
infection (2 papers, 2015 to 2018). The state of being infected such as from the introduction of a foreign agent such as serum, vaccine, antigenic substance or organism. "Our results also indicated the downregulation of certain proteins after infection with H37Ra such as inactive rhomboid protein 2 (RHBDF2), canopy-2 (CNPY2), hypoxia upregulated protein 1 (HYOU1), and protein transport protein sec23A (SC23A)." (PMID 25785198, 2015).
metabolic disorders (2 papers, 2019 to 2021). "Studies have shown that CNPY2 plays a key role in ERS and is involved in the development of many diseases, including metabolic disorders and inflammation." (PMID 31625681, 2019).
neurological diseases (2 papers, 2024 to 2026). "It will be important in the future to study the roles of CNPY2 in vivo using gene deleted animals and other models of neurological diseases." (PMID 39359687, 2024).
brain diseases (1 paper, 2024). "CNPY2 enhances neuronal survival by reducing ER stress and is a promising factor to consider in HD and possibly in other brain diseases." (PMID 39359687, 2024).
CNPY2 also shares sentences with these, for which no sentence is quoted: esophageal squamous cell carcinoma (3 papers); acute coronary syndrome (1); Alpha-thalassemia (1); anemia (1); cardiac hypertrophy (1); cardiovascular disease (1); Cerebral ischemia (1); chronic kidney disease (1); Cirrhosis (1); Diamond-Blackfan anemia (1); Fanconi anemia (1); hepatocellular carcinoma (1); ischemia (1); ischemic stroke (1); liver (1); metastatic tumors (1); microcytic anemia (1); myocardial ischemia (1); Obesity (1); pheochromocytoma (1).